CSF1R (colony stimulating factor 1 receptor)
Diseases named in the same sentence as CSF1R in open-access papers (continued):
Sharing a sentence is not in itself a finding about the gene and the disease.
cancer (continued). "For example, the half-life of the colony stimulating factor 1 receptor (CSF-1R) in macrophages is less than 1 h, whereas for the epidermal growth factor receptor (EGFR) in carcinoma cells, it is 24 h." (PMID 31600876, 2019). "Cancer cells, in turn, express CSF1, which acts as a chemoattractant and chemokinetic molecule for CSF1R-expressing TAMs." (PMID 29584702, 2018). "Additionally, cancer cells may consume IL-34 in certain subtypes at the same time, since CSF-1/CSF-1R but not IL-34 were strongly associated with stromal- and immune-score in HER2 and basal subtypes." (PMID 29796177, 2018). "First, we compared IL-34,CSF-1, CSF-1R, PTPRZ1, and SDC1 gene expression between human MCF7, SK-BR-3 and MDA-MB-231 cancer cells in comparison to human THP-1 macrophages." (PMID 29796177, 2018). "Therefore, CSF-1R might be an effective target for anti-cancer therapy." (PMID 29228668, 2017). "In context of these findings and our results, it will be very important to further investigate the effect of anti-CSF-1R treatment on different cell types of the MPS system and to establish predictive biomarkers in cancer patients." (PMID 26098772, 2015). "The real-time qPCR confirmed the CCL2, CCL3, CD163, CSF1R, MMP9, HIF1, VEGF-C up-regulation in cancer cells grown as a co-culture with macrophages." (PMID 22353646, 2012). "Under co-culture conditions the cancer cells express the macrophages-specific antigens, e.g. CD14, CD64, CD163, CSF1R." (PMID 22353646, 2012). "BLZ945 had no obvious inhibitory effects on astrocytes, endothelia and 4T1-BR5 or 231-BR cancer cells in vitro in agreement with their lack of CSF-1R expression." (PMID 40760255, 2025). "The combination of Trastuzumab and CSF1R inhibition to deplete non-cytotoxic macrophages significantly enhances ATG9A KO cancer cell killing in vivo." (PMID 40595560, 2025). "However, the journey from bench to bedside is intricate and demands continued investigation, not only into the combined therapeutic potential of LNCs@CSF1R siRNA and anti-PD-1 but also into the broader implications of MDSC regulation in various cancer types." (PMID 38992688, 2024). "Indeed, the TME of most advanced cancers is highly heterogeneous, and despite the existence of drugs that target the TME, such as anti-CSF-1R and anti-ly6g antibodies, these drugs address resistance in only a small percentage of patients." (PMID 38898505, 2024). "Also, in most of the cancers, there was a significant correlation between UBE2C gene expression and CD96, CD274, CSF1R, KDR, and PDCD1LG2." (PMID 38577722, 2024). "CSF1R is a type III receptor tyrosine kinase (RTK) that is involved in the proliferation, differentiation, survival, motility, and function of myeloid cells and in promoting disease progression in various conditions ranging from inflammation to cancer." (PMID 38480935, 2024). "CSF1R-derived PI3K-AKT pathway induces c-myc gene expression, leads to upregulation of cyclinB, cyclinD, cyclinA and CDKs which drives cell cycle resulting in cancer cell proliferation and survival." (PMID 38822100, 2024). "Interestingly, a robust correlation between the expression of CSF1R and AMIGO2 in cancer and paracancer tissue are also identified." (PMID 38189855, 2024). "Colony-stimulating factor 1 receptor (CSF1R), also known as c-FMS, CD115, or M-CSFR, is one of the most important receptors in type III RTKs and is increasingly becoming a promising target for cancer therapy." (PMID 36770611, 2023). "In addition, CSF1R antibodies (such as Emactuzumab) are also developed to block the CSF1-CSF1R pathway and showed efficacy on TAMs reduction in diffuse-type giant cancer cells." (PMID 37443711, 2023). "FACS staining confirmed that Pax5 was markedly decreased in BM CD93+ BMBP, particularly in CSF1R+ but not CSF1R− subsets, from mice with 4T1.2 or Mogp cancers." (PMID 36104343, 2022).
cancer (continued). "Our research shows that low expression of VCAN can significantly improve the survival time of HCC patients, which implied that VCAN may be the downstream or upstream target of CSF1R in HCC, and is partly involved in its cancer-promoting effect." (PMID 35812745, 2022). "Moreover, LEF1, RUNX2, CSF1R, VAV3, and FZD3 have been reported to take part in the development of cancer." (PMID 35340229, 2022). "We also described the molecular mechanism of AAM polarization and therapeutic strategies for cancer-promoting AAM macrophages, including CCL2 monoclonal antibodies or CSF1R inhibitors, AAM re-acclimation targeting immune checkpoints, and new strategies to improve the “phagocytic ability” of cells." (PMID 36439090, 2022). "Colony stimulating factor 1 receptor (CSF-1R) is a single channel III transmembrane receptor tyrosine kinase (RTK) and plays an important role in immune regulation and the development of various cancer types." (PMID 35444953, 2022). "Second, splenic transitional B cells from naïve mice do not generate B-MF regardless of their CSF1R expression state, as cancer first needs to mobilize BMBP into circulation as the source of B-MF." (PMID 36104343, 2022). "Moreover, alterations to signaling molecules upstream of these transcription factors, including CSF1R, PI3Kγ, or the SRC kinase HCK, are currently exploited to limit alternative macrophage polarization as adjuvant therapy for cancer." (PMID 36552868, 2022). "In addition, the mRNA data in the Cancer Cell Line Encyclopedia database showed that the expression of C1QC, CSF1R, LAPTM5 and SLCO2B1 mRNA was significantly lower in LUSC cell lines (n=23) compared to lymphoid cell lines (n=167)." (PMID 33428598, 2021). "However, the correlation between CSF1R/DAPK1 signalling pathways and cancer progression provides motives to reprofile them against cancer therapy." (PMID 31809612, 2020). "Blockade of CSF1R with PLX3397 induced clinical regression in patients and decreased the intratumoral accumulation of immunosuppressive macrophages, thus confirming the validity of TAMs as a therapeutic target in cancer therapy." (PMID 31805946, 2019). "Overexpression of other cancer-immunity cycle markers were also observed including myeloid suppression markers (e.g. CCL2, CCR2 and CSF1R; 10-22%), metabolic immune escape markers (e.g. ADORA2A and IDO1; 9-16%) and T-cell primed markers (e.g. CD40, GITR, ICOS and OX40; 4-26%)." (PMID 30400835, 2018). "As our understanding of the influence of CSF1/CSF1R-mediated signaling on human myeloid-derived cells other than macrophages is just emerging, the focus of this review is on TAM and current clinical efforts to specifically target CSF1/CSF1R in cancer therapy." (PMID 28716061, 2017). "Up-to-date there are no available reports regarding the impact of CSF-1R on apoptosis in cancer cells." (PMID 23561040, 2013). "We also observed that serum-starved conditions (RPMI-1640 without addition of FBS) caused a significant decrease in the mean expression and phosphorylation of CSF-1R in cancer cells, whereas it did not affect the number of cells expressing CSF-1R." (PMID 23561040, 2013). "Cancer cells culture in serum-starved conditions (RPMI-1640 without addition of FBS) decreased the mean expression of CSF-1R 1.17-2.29 fold." (PMID 23561040, 2013). "CSF1R was thought to function at the plasma membrane, but recent evidence showed the presence of functional receptor for MCSF at the nuclear envelope of various cancer cells and macrophages." (PMID 24391839, 2013).
cancer (continued). "For the purposes of the microarray data validation, we have selected 9 genes that may play the most important role in cancer cells-macrophages interactions: CCL2, CCL3, CD163, CSF1R, HIF1, Il-18, MMP9, VEGF-C, and Wnt7b." (PMID 22353646, 2012). "However, considering the fact that the major TSGCT components are mono/macrophage lineages expressing CSF1R, outweighing the small portion of cancer cells with CSF1 autocrine and paracrine, CSF1R inhibitors have been designed to selectively target TSGCT non-neoplastic components to shrink tumors." (PMID 40563544, 2025). "The most-cited paper among the 134 articles was Pexidartinib, a Novel Small-Molecule CSF-1R Inhibitor for TGCT: Systematic Review of Preclinical and Clinical Development, published by Brooke Benner at the Ohio State University Comprehensive Cancer Center in 2020." (PMID 41267978, 2025). "Thus, this review focuses on the expression and function of the CSF-1R in the various cellular components of the TME and analyzes the emerging role of CSF-1R/CSF-1R ligands in the crosstalk between infiltrating immune cells, stromal, and cancer cells." (PMID 39457693, 2024). "The CSF-1R is present on all myeloid cells and is essential for normal monocyte development and tissue macrophage homeostasis, therefore its systemic delivery is not an optimal approach for treatment of cancer." (PMID 36982211, 2023). "Interestingly, among pan-cancer, LGG showed the most significant correlation between GLA with CD86 (P=4.52e-27), CSF1R (P=8.17e-09),CCL2 (P=3.98e-14), CD68 (P=2.37e-34), IL10 (P=3.29e-21), IRF5 (P=8.5e-25), CD163 (P=3.8e-26), VSIG4 (P=9.17e-16) and MS4A4A (P=1.39e-21)." (PMID 37057282, 2023). "The lack of CSF-1R results in the metastasis of cancer cells." (PMID 36770929, 2023). "For example, blocking the binding of colony-stimulating factor 1 (CSF-1) to its receptor (CSF-1R) expressed on monocytes/macrophages with an anti-CSF-1R antibody, Emactuzumab, reduced the number of infiltrated TAMs and increased the CD8+/CD4+ T cell ratio in mouse models for cancer." (PMID 37046671, 2023). "The expression of CSF1R had no prognostic impact in all three types of patients with cancer." (PMID 37586318, 2023). "TAM membrane-coated nanoparticles could scavenge CSF1 secreted by cancer cells due to the high CSF1R content on the TAM membranes, blocking the interaction between TAMs and cancer cells and thereby enhancing the efficacy of the nanoparticles for cancer immunotherapy." (PMID 35216342, 2022). "CSF-1R is a tyrosine kinase CSF receptor expressed on macrophages that binds macrophage colony-stimulating factor (MCSF) secreted by cancer cells to drive differentiation to an M2 phenotype; thus, blocking it skews the M1 to M2 ratio towards the M1 lineage and enhances phagocytosis of cancer cells." (PMID 36429020, 2022). "The cancer target PDB ID 1RY0 (AKR1C3) showed the highest interactions with the majority of the NCs, followed by 1HFQ (DHFR), 3ZGC (NFE2L2), 4AF3 (AURKB), 4K33 (FGFR3), 5P21 (HRAS), 2I0V (CSF1R), and 3ZIM (PIK3CA) protein targets and least interaction was found with the 1M9Z (TGFBR2) protein." (PMID 36387366, 2022). "However, the functionality and biological effects of CSF-1R in prostate cells have not been investigated yet, unlike in other types of cancers." (PMID 36555673, 2022). "Notably, TIE1, KIT, NTRK1, FGFR3, CSF1R, and INSRR were shared by both cancers." (PMID 34944663, 2021). "However, the mechanism of CSF-1 and CSF-1R in GI malignant tumors is still not clear, and the mechanism of how inflammatory immune cells participate in the occurrence and development of malignant tumors is not perfectly defined." (PMID 34729112, 2021). "Preclinically, inhibition of CSF1R using monoclonal antibodies (mAbs) or small molecule drugs, such as BLZ945 and PLX3397, have been used to treat malignancies including breast, ovarian, brain, pancreatic and other cancers where they decrease TAM accumulation and promote tumor growth inhibition." (PMID 33986740, 2021).
cancer (continued). "In addition, a significantly positive correlation (p < 0.001) is also observed between CSF-1R+ carcinoma cells and macrophages expressing CSF-1R and CD163, supporting the plausible existence of a CSF-1/CSF-1R paracrine signaling mechanism as has been suggested in the preclinical studies." (PMID 34830923, 2021). "However, recent clinical trials targeting CSF1R in inflammatory diseases or cancer have not been promising." (PMID 32801364, 2020). "However, systemic CCR2 inhibition did not reduce the number of early circulating cancer cells (eCCCs) compared to the treatment that blocked the CSF1R, which reduced intra-epithelial macrophages by ~77%." (PMID 29295986, 2018). "A variety of small molecules and monoclonal antibodies (mAbs) directed at CSF1R or its ligand CSF1 are in clinical development both as monotherapy and in combination with standard treatment modalities such as chemotherapy as well as other cancer-immunotherapy approaches." (PMID 28716061, 2017). "Similarly, culture of cancer cells in serum-starved conditions (RPMI-1640 without addition of FBS) did not affect the number of cells expressing CSF-1R." (PMID 23561040, 2013). "However, the role of CSF-1R in canine mammary tissue or cancer has not been investigated yet." (PMID 23561040, 2013). "In this context, the colony-stimulating factor-1 receptor CSF1R and the non-receptor tyrosine kinase and Arg/Abl2 are important players in regulating the invasion-proliferation switch in cancer." (PMID 33490081, 2020). "On the other hand, CSF1R showed a minimal influence on the gene expressions of the whole network, thus suggesting that its inhibition should not affect the survival of the MDA-MB-231 cancer cells." (PMID 31312514, 2019).
infection (89 papers, 2008 to 2025). The state of being infected such as from the introduction of a foreign agent such as serum, vaccine, antigenic substance or organism. "Mice treated with CSF1R antagonist prior to infection exhibited higher susceptibility to lethal WNV infection and lack of virologic control in both the CNS and periphery." (PMID 30704498, 2019). "At this concentration, we found an infection phenotype similar to that of csf1r deficiency: increased bacterial cording and growth following upon granuloma formation." (PMID 26159717, 2015). "Further studies are warranted to determine whether plasma TGFBI and CSF1R are associated with infection/inflammation-related preterm birth, given the exclusion of women with infectious and inflammatory etiologies of SPTB in the present study." (PMID 34710180, 2021). "In response to either Aβ pathology or MA10 infection, microglia shared only four significantly down-regulated DEGs (Csf1r, P2ry12, Cx3cr1, Hexb), all of which are signature microglial homeostatic markers." (PMID 41497643, 2025). "A separate study which also used CSF1R antagonism to deplete microglia prior to infection confirmed the critical role of microglia in controlling infection and overall survival." (PMID 38140641, 2023). "Infection increased expression of the proinflammatory cytokine Tnf, in a manner indicative of microglia activation and systemic treatment with a CSF1R antagonist partially reversed the effect of infection on OL-specific transcripts." (PMID 37596606, 2023). "Differences between different treatments at the same sampling points on the expression of il-34 and csf-1r resulted in augmented values on fish injected with bacteria especially 48 h after infection." (PMID 35163486, 2022). "More importantly, we show increases in the mRNA expression levels of B cell (i.e., IgT, IgM, and IgD), T helper cell (i.e., CD4-1, CD4-2, and TCRα), and macrophage (i.e., MHC-II, MPEG1, and CSF1R) markers in trout SB upon infection with IHNV." (PMID 35379790, 2022). "In summary, this work provides evidence that the CSF1R-microglia axis is a critical orchestrator of the acute antiviral response to TMEV in B6J mice whereas the axis is more important in chronic stage of infection in SJL mice." (PMID 34566948, 2021). "To understand when CSF1R signaling is important in the CNS antiviral response to sustained TMEV infection, we inhibited CSF1R at different distinct phases of infection in SJL mice." (PMID 34566948, 2021). "We tested the early infection outcome in mice transiently depleted of dermal TRMs following treatment with M279, an antibody to colony stimulating factor-1 receptor (CSF-1R)." (PMID 33137149, 2020). "The identification of CSF1R+ macrophages/monocytes as a local source of C3 during infection is also critical, as these cells are recruited to the cornea in the early stages of HSV-1 infection and are associated with corneal nerve damage in HSV-1 keratitis." (PMID 31414985, 2019). "Pharmacological inactivation of CSF1R was achieved using PLX5622 prior to infection with virulent or attenuated strains of West Nile virus (WNV), an emerging neuropathogen." (PMID 30704498, 2019). "C57BL/6J mice were treated with anti-CSF1R or isotype control Ab prior to infection with Giardia and throughout the 7-d infection." (PMID 31455692, 2019). "For this we analyzed again the Th17 response to C. albicans in Flt3L-deficient animals and we included a group, in which we blocked the CSF1R prior to infection." (PMID 26431538, 2015). "Bladder-resident macrophages were eliminated by administration of anti-CSF1R depleting antibody 24 hours prior to infection." (PMID 26182347, 2015). "Next we tested the effect of reducing both macrophage supply and demand by assessing ESX-1 infection in csf1r mutant hosts." (PMID 26159717, 2015).